NEAT1 (nuclear paraspeckle assembly transcript 1)
Diseases named in the same sentence as NEAT1 in open-access papers (continued):
Sharing a sentence is not in itself a finding about the gene and the disease.
viral infection (49 papers, 2012 to 2025). "In our data, we also found several DE-lncRNAs that have been reported to be associated with viral infections, such as NEAT1." (PMID 40285022, 2025). "Specifying which isoform of NEAT1 is responsible for the regulation will not only help determine the underlying mechanisms but also help develop therapeutic strategies against viral infections and other pathogens that threaten humans." (PMID 40362651, 2025). "Virus infection exerts significant influence on the cellular transcriptome, causing changes in the expression of long non-coding RNAs (lncRNAs) such as NEAT1." (PMID 38717150, 2024). "In this context, metastasis associated lung adenocarcinoma transcript 1 (MALAT1) and nuclear paraspeckle assembly transcript 1 (NEAT1) are two lncRNAs implicated in neurodegenerative process and viral infection, also in association with TDP-43." (PMID 36675095, 2023). "For example, lncRNA NEAT1 is associated with the expression of IL-8, eventually affecting the virus infection." (PMID 33472590, 2021). "In response to either proteasomal inhibition or viral infection, NEAT1 RNA abundance increases > 4 fold, causing significant paraspeckle enlargement and sequestration of SFPQ." (PMID 33898516, 2021). "Although changes in NEAT1 expression have been implicated in several different viral infections, few studies have focused on the potential roles of NEAT1 in viral replication and viral gene expression." (PMID 27783096, 2017). "We found that in human cells 75 long intergenic noncoding RNAs (lincRNAs) were differentially expressed (38 up-regulated, 37 down-regulated) in response to IFN, including NEAT1, a lincRNA that has previously been associated with viral infections." (PMID 29253856, 2017). "Additionally, the expression of NEAT1 positively correlates with the severity of the virus infection risk." (PMID 40362651, 2025). "In our study, we focus on measuring the expression levels of two ncRNAs (NEAT-1 and miR-374b-5p) due to the following causes: both NEAT-1 and miR374b-5p are pro-inflammatory molecules that affect innate immune responses, which is the first line of defense of the host against viral infection." (PMID 39729489, 2024). "NEAT1 lncRNA has also been associated with viral infection, namely, HIV-1." (PMID 33138195, 2020). "Considering that NEAT1 expression is induced upon virus infection, it would be intriguing to study whether the NEAT1 knockout mice show increased or decreased susceptibility to viral infections." (PMID 22476590, 2012). "Thus, we determined whether the upregulation of NEAT1 by viral infection was associated with NF-κB/IL-6 signaling." (PMID 41208976, 2025). "NEAT1 is one of the most studied disease-linked lncRNAs, and its modulation may provide benefit in a wide range of human conditions, from cancer to neurodegenerative diseases and viral infections." (PMID 36099417, 2022). "Studies show that NEAT1 can be upregulated in immune cells in response to viral infection and promotes innate immunity against viral attack through various mechanisms." (PMID 40362651, 2025). "Viral infections directly induce the expression of NEAT1, resulting in an immune response against the virus." (PMID 40362651, 2025). "The upregulation of NEAT1 by virus infection and its positive correlation with the severity of immune-related diseases suggest that NEAT1 can serve as a biomarker for these conditions." (PMID 40362651, 2025). "The research also explores the potential of NEAT1-targeted RNA-based therapies for managing viral infections and preventive approaches." (PMID 40144645, 2025). "To date, two different pathways were shown to be involved in the induction of NEAT1 expression in response to viral infection." (PMID 38717150, 2024). "In a viral infection, gel containing NEAT1-siRNA reduced the activity of inflammatory macrophage and promoted HTNV propagation." (PMID 37310654, 2023).
viral infection (continued). "In general, up-regulation of lncRNA NEAT1 expression appears to be a general response to viral infection." (PMID 36560611, 2022). "In NEAT1 knockdown or knockout contexts, failure to transcriptionally regulate these mRNAs correctly following proteasomal inhibition or viral infection leads to increased cell death and impaired innate immune responses, respectively." (PMID 33898516, 2021). "And it was well identified that NEAT1 was involved in multiple physiological and pathological processes, including transcriptional regulation, alternative splicing, virus infection, neuronal activity, tumor microenvironment regulation and immune response." (PMID 33680941, 2020). "Upon viral infection, NEAT1 expression is induced leading to a NEAT1‐dependent relocation of PSF/SFPQ from the IL‐8 promotor to paraspeckles activating IL‐8 transcription and subsequent stimulating immune response." (PMID 30430751, 2019). "In a viral infection, NEAT1 sequesters the IL-8 repressor PSF/SFPQ from the IL-8 promoter to paraspeckles." (PMID 30717168, 2019). "The expression of Neat1 is also induced by certain viral infections and facilitates the expression of antiviral cytokines such as IL-839." (PMID 31673072, 2019). "Over the last two years, numerous viral diseases have been correlated with differences in NEAT1 expression, either acting anti-viral or pro-viral." (PMID 30717168, 2019). "To test this, we used a viral infection mimic, synthetic dsRNA poly(I:C), a pathophysiological stimulus reported to enhance NEAT1 synthesis and paraspeckle formation." (PMID 30642400, 2019). "Summarizing recent data pertaining to NEAT1, one can draw the conclusion that this lncRNA contributes to regulating viral diseases and neurodegeneration." (PMID 30717168, 2019). "Although increased NEAT1 levels seem to be a common event upon viral infection and in neurodegenerative diseases, the consequences of NEAT1 upregulation are diverse." (PMID 30717168, 2019). "In response to viral infection, induction of NEAT1 results in relocation of SFPQ from the IL-8 promoter to paraspeckles followed by triggering transcriptional activation of IL-8." (PMID 28465674, 2017). "It has been reported that NEAT1 is induced in host cells by viral infection, including HSV-1 infection." (PMID 27783096, 2017). "Here, the human umbilical vein endothelial cell (HUVEC) transcriptome was analyzed after HTNV infection by digital gene expression (DGE) profiling, and lncRNA NEAT1 was found to be remarkably upregulated by viral infection." (PMID 28202761, 2017). "LPS treatment also induces the expression of lncRNA NEAT1, which has been shown to be activated in viral infections and is responsible for transcription of inflammatory cytokines through the TLR4 signaling pathway." (PMID 29147069, 2017). "Taken together, lncRNA NEAT1 plays an important role in the innate immune response to viral infection." (PMID 28465674, 2017). "As a stress-induced lncRNA, the expression of NEAT1 increases in response to viral infection, but little is known about the role of NEAT1 or paraspeckles in the replication of herpes simplex virus-1 (HSV-1)." (PMID 27783096, 2017). "It has been shown that NEAT1 is induced by viral infection as well as by poly I:C stimulation and that, in response to such a stimulus, NEAT1 binds to paraspeckle protein splicing factor proline/glutamine-rich (SFPQ)." (PMID 25368617, 2014). "Together, these data indicate that NEAT1 could be a promising therapeutic target for treating viral diseases." (PMID 41208976, 2025). "NEAT1 can also regulate innate immune responses induced by viral infections." (PMID 40285022, 2025). "Some studies have indicated that NEAT1 may function as a potential therapeutic target for viral infection." (PMID 41208976, 2025). "Finally, NEAT1 appears as a dual regulator of viral infection, exhibiting both pro-viral and anti-viral effects depending on the context." (PMID 38717150, 2024).
viral infection (continued). "NEAT1, the scaffold lncRNA of paraspeckles, has emerged as another player in viral infections." (PMID 38717150, 2024). "NEAT1 principally regulates subnuclear paraspeckles in nuclei, and paraspeckles and their family members can play a role in several biological processes, including cell differentiation, the response to viral infection, and oxidative stress." (PMID 38699233, 2024). "The presence of NEAT1 in plasma has been suggested as a biomarker for viral infection." (PMID 38179937, 2024). "NEAT1 upregulation is a general response to viral infections." (PMID 36099417, 2022). "Further studies have found that NEAT1 promotes HIV-1 replication, suggesting that NEAT1 may play a key role in responding to viral infection." (PMID 33710444, 2021). "As a stress-induced lncRNA, NEAT1 expression increases in response to a viral infection." (PMID 30717168, 2019). "Therefore, the effect of viral infection on the formation of paraspeckles is probably attributable to the increase in NEAT1 expression, which facilitates the organization of the paraspeckle components." (PMID 27783096, 2017). "Nevertheless, studies assessing the function of NEAT1 in viral infections are scarce." (PMID 28202761, 2017). "Investigative studies on the same long non-coding RNA have emphasized the role of NEAT1 in paraspeckle formation and have been further hypothesized to be an essential component in the host responses to viral infections." (PMID 28465674, 2017). "Moreover, treatment with TLR3 ligand poly I:C mimics the effect of viral infection on stimulation of lncRNA NEAT1 expression." (PMID 28465674, 2017). "Using an RNA fluorescence in situ hybridization (FISH) assay, we found that HSV-1 infection increases the number of NEAT1 puncta, suggesting that viral infection induces the formation of paraspeckles, possibly by increasing the expression of NEAT1, which is the organizer of paraspeckles." (PMID 27783096, 2017). "Since viral infection induced NEAT1 expression immediately within a few hours post-infection, we speculated that innate immune signaling pathway may regulate the expression of NEAT1 during viral infection." (PMID 41208976, 2025). "Therefore, whether there is a regulatory feedback loop between NEAT1 and cytokines during viral infection warrants future investigations." (PMID 40362651, 2025). "All these studies highlight that NEAT1 may serve as a biomarker for viral infections." (PMID 40362651, 2025). "Notably, our RNA-Seq analysis displayed that expression levels of type I IFNs and some antiviral molecules, which play roles in restricting viral infections, were significantly reduced in NEAT1 knockdown A549 cells as compared to the control cells upon IAV infection." (PMID 41208976, 2025). "For example, nuclear enriched abundant transcript 1 (NEAT1) is the core element of paraspeckles that participate in various biological processes such as nuclear retention of adenosine-to-inosine-edited mRNAs to restrict their cytoplasmic localization and viral infection response." (PMID 32093746, 2020). "Therefore, we investigated whether the increase in NEAT1 expression induced by viral infection is mediated by STAT3." (PMID 27783096, 2017). "Given NEAT1 established role in viral infection response, we analyzed its main transcript (ENST00000501122.2, NEAT1-001, 22 743 nt)." (PMID 41267684, 2025). "For example, lnc-ISG20 and ISR function as interferon-stimulated genes (ISGs), and LncRNA-155, NEAT1, SAAL, RDUR, AVAN and IVRPIE can suppress IAV replication by promoting innate immune responses to viral infection." (PMID 37308824, 2023). "NEAT1 is documented as a virus inducible non‐coding RNA (VINC), and changes in NEAT1 expression have been investigated in several different viral infections." (PMID 30924966, 2019).
viral infection (continued). "Taken together, our findings demonstrate that NEAT1 modulates the innate immune response against HTNV infection, providing another layer of information about the role of lncRNAs in controlling viral infections." (PMID 28202761, 2017). "It has been reported that upon virus infection, levels of NEAT1 were induced to sequester PSF, the transcriptional repressor of an antiviral gene interleukin-8, activating the innate immune response against viral infection." (PMID 28288210, 2017). "Similarly, notwithstanding the role of NEAT1 and PSF in inflammation and activation of the innate immune response, the paraspeckles’ effects on viral infection are pathogen-specific." (PMID 36081760, 2022). "Whereas the downregulation of lncRNA PVT1 seems to protect pancreatic β cells from injury, both up-regulated MALAT1 and NEAT1 had been related to inflammatory mediators (TNF-alpha, IL-6, CXCL10), SLE pathogenesis and innate immune response against viral infections." (PMID 35058920, 2021). "This review summarizes recent literature about the role of the lncRNA nuclear enriched abundant transcript 1 (NEAT1) in non-cancerous diseases with a special focus on viral infections and neurodegenerative diseases." (PMID 30717168, 2019). "NEAT1 is induced by IAV infection, and this relocates SFPQ to the paraspeckle, thereby eliminating its transcriptional repression of interleukin-8 (IL-8) expression and thus activating an innate immune pathway in response to viral infection." (PMID 30429226, 2018). "Although the role of NEAT1 in immune system function, especially during viral infection (e.g., human immunodeficiency viral infection), has been intensely investigated, its function of NEAT1 in neutrophils has not been fully addressed." (PMID 26552600, 2015).
glioblastoma (47 papers, 2016 to 2026). The most malignant astrocytic tumor (WHO grade IV). "that NEAT1 was a risk factor facilitating immune evasion in glioblastoma." (PMID 39720765, 2025). "NEAT1 silencing has remarkably promoted TMZ-associated cell apoptosis in glioblastoma cells." (PMID 34178658, 2021). "NEAT1 functions as a scaffold RNA by interacting with different target genes and acts on transcriptional activation of various genes associated with cancer, including glioblastoma." (PMID 32283739, 2020). "An association between GJA1 and NEAT1 expression in GBM samples was observed in the analysis of glioblastoma samples, showing a Pearson correlation coefficient of 0.245." (PMID 39453684, 2024). "Targeting NEAT1 in GSCs presents an avenue for sensitizing these cells to conventional therapies and enhancing treatment outcomes in glioblastoma." (PMID 39015773, 2024). "In this study, we employed an isoform-specific quantification assay and found differential dysregulation of NEAT1 isoforms in patient-derived glioblastoma multiforme cells." (PMID 39032650, 2024). "By bolstering GSCs and undermining the efficacy of standard treatments, NEAT1 contributes to tumor progression and unfavorable patient outcomes in glioblastoma." (PMID 39015773, 2024). "For instance, ALKBH5 stabilized lncRNA NEAT1 transcript via m6A demethylation and thus facilitated lncRNA NEAT1-mediated paraspeckle assembly, ultimately promoting glioblastoma multiforme progress through upregulating downstream CXCL8/IL8 pathway." (PMID 38145297, 2024). "NEAT expression was associated with immune checkpoint blocker therapy in glioblastoma (GBM) patients and increased NEAT1 expression in M1 polarized macrophages led to secretion of inflammatory cytokines." (PMID 39198884, 2024). "Further, we examined NEAT1 expression in human glioblastoma cells (U87MG and A172) and human astrocytes (NHA)." (PMID 39453684, 2024). "Nuclear enriched abundant transcript 1 (NEAT1) has emerged as a pivotal regulator in GSCs and thus a promising therapeutic target for glioblastoma." (PMID 39015773, 2024). "The last hub lncRNA NEAT1 promotes glioblastoma development and progression through the EGFR/NEAT1/EZH2/WNT/β-catenin axis." (PMID 36090045, 2022). "GAS8-AS1 overexpression inhibits GBM cell proliferation and invasion by downregulating NEAT1 and achieves the purpose of inhibiting the proliferation of glioblastoma cells." (PMID 35371346, 2022). "Interacting with several common genes and miRNAs in complex axis, NEAT1 regulates, other than normal cellular processes such as apoptosis and cell cycle, also tumorigenesis in glioblastoma." (PMID 35814429, 2022). "Other investigators noted that in glioblastoma, lncRNA NEAT1 bound to the histone methyltransferase enhancer of zeste homolog 2 (EZH2) and subsequently inhibited the expression of its downstream target genes." (PMID 33901015, 2021). "A recent study revealed that lncRNA NEAT1 is an oncogene in glioblastoma, which promotes cell growth and invasion by increasing β-catenin nuclear transport." (PMID 34681857, 2021). "NEAT1 functions as a sponge for several tumor suppressor miRNAs in glioblastoma and influences critical pathways such as Wnt." (PMID 33466745, 2021). "In summary, the EGFR/NEAT1/EZH2/β-catenin axis plays a crucial role in the development of glioblastoma." (PMID 32283739, 2020). "Recently, decreased NEAT1 expression was reported to inhibit Wnt/β-catenin signaling pathway activity in glioblastoma." (PMID 30185232, 2018). "Additionally, the STAT3 pathway is described as upstream of NEAT1, binding to and activating the NEAT1 promoter in glioblastoma." (PMID 40170567, 2025). "Also, it has been reported that NEAT1 knockdown increases the chemosensitivity of glioblastoma cells to temozolomide." (PMID 39010056, 2024). "NEAT1 expression was markedly increased in glioblastoma cells compared to NHA." (PMID 39453684, 2024).